IL37 (interleukin 37)
Diseases named in the same sentence as IL37 in open-access papers (continued):
Sharing a sentence is not in itself a finding about the gene and the disease.
rheumatoid arthritis (50 papers, 2014 to 2025). A chronic, systemic autoimmune disorder characterized by inflammation in the synovial membranes and articular surfaces. "Clinical studies have demonstrated that IL-37 gene variant rs3811047 G > A is associated with susceptibility to rheumatoid arthritis and ankylosing spondylitis." (PMID 37853488, 2023). "To date, several studies have investigated the potential role of natural variants of the IL‐37 gene in human disease, including M. tuberculosis infection, coronary artery disease, and rheumatoid arthritis." (PMID 31755162, 2020). "The recombinant IL‐37 protein has been shown to function in wild‐type mouse models of diseases, such as ischemic injury, hepatitis, and rheumatoid arthritis, but fewer studies have reported an association of IL‐37 with bone infections." (PMID 30414292, 2019). "Increased IL-37 levels have been associated with many autoimmune and chronic inflammatory diseases, such as rheumatoid arthritis, systemic lupus erythematosus, and Guillain-Barré syndrome in humans." (PMID 26504600, 2015). "Patients with rheumatoid arthritis demonstrated an increased level of synovial IL-1R8, which is essential for the anti-inflammatory effects of IL-37." (PMID 35935954, 2022). "The high-frequency keywords include “expression”, “IL-37”, “inflammation”, “cytokine”, “IL-1 family”, “cell”, “immunity”, “receptor”, “rheumatoid arthritis”, and “activation”." (PMID 35935954, 2022). "Not only that, it has been proven that IL-37 induces apoptosis in rheumatoid arthritis fibroblast-like synoviocytes." (PMID 35935954, 2022). "IL-37 is an anti-inflammatory factor in IL-1 family, which plays a role in lung cancer, rheumatoid arthritis and many other diseases." (PMID 36418383, 2022). "Increased levels of circulating IL-37 have been reported in the patients with rheumatoid arthritis, multiple sclerosis, and systemic lupus erythematosus." (PMID 35935954, 2022). "IL-37 has an anti-inflammatory effect in rheumatoid arthritis, reduces the secretion of IL-1β, IL-6, and TNF-α and MIP-2, and mediates M2 macrophage polarization." (PMID 34842603, 2021). "IL-37 treatment represses the proliferation and migration and induces the apoptosis of rheumatoid arthritis fibroblast-like synoviocytes (RAFLS)." (PMID 34248996, 2021). "Using murine experiments, IL-37 has been shown to play immunoregulatory roles in myocardial infarction, rheumatoid arthritis (RA), diabetes, allergic asthma, and fungal infections." (PMID 29988381, 2018). "IL-37 has been reported to exert a potent immunosuppressive role in the pathogenesis of human rheumatoid arthritis (RA) and in mice with collagen-induced arthritis (CIA) models by downregulating IL-17 and impairing of Th17 cell proliferation." (PMID 28076390, 2017). "Whether IL-37 protects from other cardiovascular diseases that are characterized by high-grade inflammation (e.g., with myocarditis or endocarditis as the underlying cause) or develop as a comorbidity of high inflammatory diseases (e.g., rheumatoid arthritis) remains a topic for future research." (PMID 28792474, 2017). "In rheumatoid arthritis, IL-37 is involved in the regulation of proliferation, production of inflammatory mediators, and activation of inflammatory cells." (PMID 29137646, 2017). "Increased levels of IL-37 have been reported in multiple diseases by measuring IL-37 mRNA or protein in cells derived from patients or in serum, such as rheumatoid arthritis, melanoma, atopic dermatitis, and ankylosing spondylitis." (PMID 28420941, 2017). "The IL-37 protein is highly expressed in synovial cells of patients with rheumatoid arthritis but expressed at low levels in healthy human synovial cells." (PMID 25214710, 2014). "The role of IL-37 has been investigated in several autoimmune diseases, including Guillain–Barré syndrome, Crohn’s disease, Graves’ disease, psoriasis, rheumatoid arthritis, systemic lupus erythematosus, and ankylosing spondylitis." (PMID 40430016, 2025).
rheumatoid arthritis (continued). "Besides, the studies have shown that IL-37 alleviates TNF-induced pyroptosis of rheumatoid arthritis fibroblast-like synoviocytes by inhibiting the NF-κB/GSDMD signaling pathway." (PMID 40704967, 2025). "IL-37, a novel member of the IL-1 cytokine family with natural anti-inflammatory properties, has been reported to play a protective role in various diseases, including cardiovascular disease, tumors, rheumatoid arthritis and pulmonary fibrosis." (PMID 38790051, 2024). "The keywords with high co-occurrence, “Inflammation”, “Dendritic cell”, “Rheumatoid arthritis”, “Pathogenesis”, and “Disease”, proved that the role of IL-37 in different cellular immune responses and immunological diseases has grown into a main focus of research in the past few years." (PMID 35935954, 2022). "In addition to mechanism research, three productive co-cited papers determined the effect of IL-37 in systemic lupus erythematosus, colitis, and rheumatoid arthritis." (PMID 35935954, 2022). "This might be due to the long list of diverse functions demonstrated by IL-37, and its active role in the physiopathology of multiple diseases including rheumatoid arthritis (RA), inflammatory bowel disease (IBD), and asthma." (PMID 29137646, 2017). "IL-37 was elevated in some inflammatory diseases such as inflammatory bowel disease, atopic dermatitis, rheumatoid arthritis, and systemic lupus erythematosus, indicating IL-37 may have potential protective effect on inflammatory diseases." (PMID 25960620, 2015). "The aim of this study was to assess the change of IL-37 concentrations in rheumatoid arthritis (RA) patients under Disease-modifying anti-rheumatic drug (DMARD) therapy, and to establish a correlation between Interleukin-37 and pro-inflammatory cytokines in plasma and disease activity." (PMID 24788826, 2014). "IL-37 has already been studied in other rheumatic diseases such as rheumatoid arthritis (RA), lupus, and ankylosing spondylitis." (PMID 40430016, 2025). "Interleukin (IL)-37, a pivotal anti-inflammatory cytokine and a fundamental inhibitor of innate immunity, has recently been shown to be abnormally expressed in several autoimmune-related orthopedic diseases, including rheumatoid arthritis, ankylosing spondylitis, and osteoporosis." (PMID 31582734, 2019). "It was found that IL-37 showed immunosuppressive response in patients with rheumatoid arthritis (RA) and in mice with collagen-induced arthritis (CIA) via suppressing IL-17 and IL-17–triggering cytokine production and limiting Th17 cell proliferation." (PMID 27941849, 2016). "IL-37 plays a potential anti-inflammatory role in rheumatoid arthritis (RA)." (PMID 39684587, 2024). "Recombinant IL-37 significantly reduced Th17 cell frequency and the expression of IL-17 in CD4+ T cells and PBMCs from patients with rheumatoid arthritis." (PMID 29137646, 2017). "This study was performed to determine whether IL-37 was elevated in patients with rheumatoid arthritis (RA) and investigate the correlation between IL-37 level and disease activity and the concentration of Th1/Th2/Th17-related cytokines." (PMID 26435567, 2015). "Up-regulated expressions of IL-37 in serum have been reported in many inflammation-related disorders, such as systemic lupus erthymatosus (SLE), rheumatoid arthritis (RA) and acute coronary syndrome." (PMID 25627863, 2015). "IL-37a, a member of the IL-37, is lacking research into its function and mechanism in rheumatoid arthritis." (PMID 39684587, 2024). "Moreover, exogenous treatment with recombinant IL-37 exerted anti-inflammatory properties in collagen-induced arthritis (CIA) models, as well as in T cells from patients with rheumatoid arthritis." (PMID 35887095, 2022).
rheumatoid arthritis (continued). "Circulating IL-37 levels have been found to positively correlate with levels of CRP and/or ESR in patients with rheumatoid arthritis, systemic lupus erythematosus, adult-onset Still’s disease, ankylosing spondylitis, gout, and osteoarthritis, as well as in patients with chronic heart failure." (PMID 34367169, 2021).
colitis (49 papers, 2008 to 2026). Inflammation of the colon. "Indeed, the protective and pathogenic functions of IL-37 during colitis were consistent with those of other members of the IL-1 family, including IL-1, IL-33, and IL-36 35-38." (PMID 35836813, 2022). "In this study, we investigated the contribution of environmental factors to shaping gut microbiota composition in colitis mice that were transgenic for human IL-37, a natural anti-inflammatory cytokine possessing pathogenic and protective functions related to microbiota alterations." (PMID 35836813, 2022). "The weighted Unifrac-based PCoA revealed that IL-37tg conventionally housed animals with DSS induction had a shift in fecal bacterial composition clustering that was distinct from WT animals, indicating that IL-37 caused the dysbiosis of gut microbiota in colitis." (PMID 35836813, 2022). "The present study provides experimental evidence that transgenics expressing human IL-37 aggravate DSS-induced colitis, which is strongly linked to intestinal barrier defects and pathogenic bacteria invasion, both of which might promote immune cell recruitment to exacerbate inflammatory responses." (PMID 35836813, 2022). "Here, we show that IL-37 alleviates colitis by reducing global m6A levels and reshaping CD4+ T-cell metabolism." (PMID 42263254, 2026). "It has been elegantly demonstrated that hemopoietic-derived IL-37 provides an essential protective role from DSS colitis, by adoptive transfer of bone marrow from IL-37 transgenic mice, compared to that of the control bone marrow." (PMID 39206201, 2024). "IL-37 up-regulation can reduce inflammation and alleviate IBD symptoms in dextran sodium sulfate (DSS)-induced colitis model, indicating that IL-37 or its regulatory factors are a promising target for IBD treatment." (PMID 38720903, 2024). "Compared to wild-type (WT) mice with colitis, the IL-37 over-expression transgenic mice showed more severe colitis and a greater number of tumors." (PMID 39206201, 2024). "We previously reported that hematopoietic-derived IL-37 from bone marrow transplantation is sufficient to ameliorate the severity of DSS-induced colitis in WT mice." (PMID 37799712, 2023). "DSS-induced colitis mouse model was used, results show that the expression level of IL-37 was significantly higher in the colon after treatment with DSS than in the steady state." (PMID 35046386, 2022). "Taken together, our study indicates that the potent anti-inflammatory properties of IL-37 are deleterious during colitis in conventional housing settings." (PMID 35836813, 2022). "Here, our findings confirmed that IL-37 has a dual effect in colitis by shaping intestinal flora composition when animals are housed in conventional or SPF conditions." (PMID 35836813, 2022). "Transgenic mice expressing human IL-37 and mice treated with IL-37 are protected from many different experimental models of inflammation, including endotoxin shock, colitis, lung injury, arthritis and inflammation-induced arthritis." (PMID 36418383, 2022). "Restoring intestinal homeostasis, on the other hand, can accomplish the protective effect of IL-37 in colitis." (PMID 35836813, 2022). "The mechanism by which IL-37 worsened colitis was studied by evaluating intestinal epithelial barrier function, immune cell infiltration, the expression of diverse cytokines and chemokines, as well as activated signaling pathways." (PMID 35836813, 2022). "These unexpected findings indicated that IL-37 was detrimental in the DSS colitis model under conventional housing environments." (PMID 35836813, 2022). "For example, IL37-Tg mice subjected to dextran sulfate sodium (DSS)-induced colitis, as well as spinal cord injury, were protected against the development of disease phenotypes." (PMID 35887095, 2022). "Here, we confirmed that anti-inflammatory cytokine IL-37 can function as a critical inducer of dysfunctional cytotoxic CD8+ T cells, thus promoted colitis-associated carcinogenesis." (PMID 35046386, 2022).
colitis (continued). "While mice do not normally express IL-37, transgenic mice with overexpressed human IL-37 are protected from lipopolysaccharide (LPS)-induced shock and dextran sulfate sodium–induced colitis." (PMID 33674380, 2021). "It has been reported that IL-37 performs a protective effect on colitis, arthritis, pancreatitis, and other inflammatory diseases which were induced by exogenous stimuli." (PMID 32733162, 2020). "IL-37tg mice are protected from dextran sulfate sodium-induced colitis and LPS-induced septic shock, whereas treatment with human IL-37 plasmid-DNA ameliorates local and systemic inflammation in psoriasis and concanavalin A-induced hepatitis." (PMID 31686988, 2019). "Despite epithelial expression, presence of IL-37 in the immune cell compartment is sufficient to protect mice from acute DSS-induced colitis." (PMID 31781119, 2019). "The histopathological colitis score in the WT DSS + IL-37+ T mice was lower than the score of the WT DSS + PBS-treated mice (p < 0.05)." (PMID 30563054, 2018). "This is in line with models of colitis where IL-37 expression also reduced the secretion of pro-inflammatory cytokines." (PMID 28792474, 2017). "In line with this, the protective effect of IL-37 expression was evident in diseases with active chronic or acute inflammation, such as colitis, inflammatory arthritis and septic shock." (PMID 28792474, 2017). "The human cytokine interleukin (IL)-37 has potent anti-inflammatory capacities, and hematopoietic cell-specific transgenic overexpression of IL-37 in mice protects against septic shock and colitis." (PMID 28792474, 2017). "IL-37 has a protective role in a murine model of lethal endotoxemia, and it has been reported that mice overexpressing IL-37 are protected from DSS colitis." (PMID 25620965, 2014). "Transgenic mice expressing human IL-37 on haematopoietic cells were protected from chemically-induced colitis and from local and systemic inflammation in ConA-induced hepatitis and LPS challenge." (PMID 25375146, 2014). "This is in line with other studies, showing that macrophages from hIL-37Tg mice produce less TNF and that IL-37 overexpression reduces TNF-dependent inflammation in a murine model of colitis." (PMID 25620965, 2014). "For example, mice transgenic for human IL-37 are protected against systemic endotoxemia, chemical induced colitis, ConA hepatitis, and ischemic reperfusion injury, as reviewed in Dinarello and Bufler (2013)." (PMID 25620965, 2014). "IL-37 transgenic mice subjected to dextran sulfate sodium (DSS)-induced colitis have significantly less clinical disease compared to wild-type mice." (PMID 23847614, 2013). "Wild-type mice reconstituted with bone marrow from IL-37 transgenic mice were protected from colitis, suggesting that IL-37 originating from hematopoietic cells is sufficient to exert protective anti-inflammatory effects." (PMID 23847614, 2013). "Conversely, under SPF conditions, IL-37 transgenic mice displayed less severe colitis." (PMID 39206201, 2024). "However, it should be highlighted that the colitis induced by IL-37 was only observed in experimental animals maintained in conventional facilities, whereas the protective effects were observed in colitis under SPF experimental settings." (PMID 35836813, 2022). "To determine whether IL-37 influences the development of colitis in conventionally housed mice, we induced acute colitis by treating conventionally housed IL-37tg mice and WT littermates with 1.5% DSS for eight days and monitoring them for an additional 24 h." (PMID 35836813, 2022). "Therefore, more severe colitis symptoms were detected in IL-37tg mice, perhaps because abundant IL-37 in colon inhibited IL-18–mediated cytoprotective effects in the DSS model." (PMID 35046386, 2022). "Therefore, to reveal the anti-inflammatory properties of IL-37, we constructed mice disease models using human IL-37 transgenic mouse models, such as endotoxemia, colitis and spinal cord injury and metabolic syndrome mice." (PMID 36002836, 2022).